ARHGEF16 (Rho guanine nucleotide exchange factor 16)
Description:
Guanyl-nucleotide exchange factor of the RHOG GTPase stimulating the exchange of RHOG-associated GDP for GTP. May play a role in chemotactic cell migration by mediating the activation of RAC1 by EPHA2. May also activate CDC42 and mediate activation of CDC42 by the viral protein HPV16 E6.
Synonyms: NBR; GEF16
Tractability: PROTAC: ubiquitination databases record sites on it.
Gene: Protein-coding gene on chromosome 1 (3,454,550 to 3,481,127, forward strand). Ensembl gene ENSG00000130762.
Subcellular location: Cytoplasm
Pathways (Reactome):
Signal Transduction: CDC42 GTPase cycle; G alpha (12/13) signalling events; NRAGE signals death through JNK; RHOG GTPase cycle
Gene Ontology:
Molecular function: cadherin binding; GTPase activator activity; guanyl-nucleotide exchange factor activity; PDZ domain binding; protein binding; receptor tyrosine kinase binding; small GTPase binding
Biological process: activation of GTPase activity; cell chemotaxis; positive regulation of protein localization to plasma membrane; regulation of Cdc42 protein signal transduction; regulation of actin cytoskeleton organization
Cellular component: cytosol; cytoplasm
Genetic constraint (gnomAD): Loss-of-function variants: 58 observed, 70.9 expected, observed/expected ratio (o/e) 0.82, 90% interval 0.66 to 1.02. The upper end of that interval is the gene's LOEUF score, 1.02, which puts it in group 4 of 6, group 1 being the genes least tolerant of losing a copy. Missense variants: 933 observed, 957.19 expected, observed/expected ratio (o/e) 0.97, 90% interval 0.92 to 1.03. Synonymous variants: 406 observed, 397.68 expected, observed/expected ratio (o/e) 1.02, 90% interval 0.94 to 1.11.
Homologues: Orthologues: chimpanzee ARHGEF16 (98% identical), macaque ARHGEF16 (96% identical), pig ARHGEF16 (83% identical), rat Arhgef16 (82% identical), mouse Arhgef16 (82% identical), dog ARHGEF16 (82% identical), guinea pig ARHGEF16 (76% identical), tropical clawed frog arhgef16 (57% identical), zebrafish arhgef16 (44% identical), Caenorhabditis elegans ephx-1 (31% identical). Paralogues in human: ARHGEF26 (46% identical), ARHGEF5 (29% identical), NGEF (27% identical), ARHGEF19 (25% identical), ARHGEF15 (25% identical), ARHGEF35 (7% identical).
Diseases named in the same sentence as ARHGEF16 in open-access papers:
ARHGEF16 is named in the same sentence as 13 diseases in open-access papers, as found by Europe PMC text mining. Sharing a sentence is not in itself a finding about the gene and the disease. The quoted sentences say what the papers report.
glioma (6 papers, 2011 to 2022). A benign or malignant brain and spinal cord tumor that arises from glial cells (astrocytes, oligodendrocytes, ependymal cells). "Promoter methylation of ARHGEF16 may therefore be involved in the formation of gliomas with loss of 1p and 19q." (PMID 21760942, 2011). "Previous studies have demonstrated that ARHGEF16 enhanced the migration and proliferation of human glioma cells." (PMID 36241648, 2022). "In combination, colony formation and EdU assays showed proliferation-promoting effects of ARHGEF16 on glioma cell proliferation." (PMID 30305138, 2018). "Cytoskeleton-associated protein 5 (CKAP5) was identified as an interaction protein of ARHGEF16, which is important for the stimulatory effects of ARHGEF16 on glioma cell migration and proliferation." (PMID 30305138, 2018). "Glioma cells U87 and U118 overexpressing ARHGEF16 showed enhanced migration and proliferation relative to the control cells, while knockdown of ARHGEF16 in H4 cells led to decreased cell proliferation compared to the control H4 cells." (PMID 30305138, 2018). "In contrast to the increased migration and proliferation capacities of ARHGEF16-overexpressing U87 or U118 cells, ARHGEF16 knockdown in H4 cell greatly inhibited glioma cell proliferationas assessed via plate colony formation and EdU assays." (PMID 30305138, 2018). "It has been verified that circRNAs and their host genes could be regulated by the common transcription factor and Gli2 was previously verified to transcriptionally activate ARHGEF16 in glioma cells." (PMID 32493490, 2020). "In this study, we identified ARHGEF16 as a target gene of GLI2 that interacts with cytoskeleton-associated protein 5 (CKAP5) to regulate glioma cell migration and proliferation, thus promoting glioma progression." (PMID 30305138, 2018). "Furthermore, the effects of GLI2 inhibition on glioma growth were supported by the lower protein levels of ARHGEF16 as well as Ki67 and MMP9 in GLI2A, GANT61 group than in GLI2A, vehicle group, as determined by immunohistochemistry." (PMID 30305138, 2018). "Our results indicate that the GLI2/ARHGEF16/CKAP5 axis promotes glioma progression by enhancing tumor cell migration and proliferation and could therefore serve as a therapeutic target for glioma treatment." (PMID 30305138, 2018). "Thus, CKAP5 acts in conjunction with ARHGEF16 to promote glioma cell migration and proliferation induced by GLI2." (PMID 30305138, 2018). "Accordingly, we found that ARHGEF16 enhanced migration and proliferation in glioma cells." (PMID 30305138, 2018). "In this study we identified ARHGEF16 as a target gene of GLI2 in glioma cells." (PMID 30305138, 2018). "Moreover, cell migration and proliferation were enhanced in GLI2A + sh-Control U87 cells relative to Control+sh-Control U87 cells, suggesting that GLI2 promotes glioma cell migration and proliferation through ARHGEF16." (PMID 30305138, 2018). "ARHGEF16 lies on 1p36 a region that is commonly deleted in gliomas." (PMID 21760942, 2011). "For in vivo study, given the weak oncogenic capacity of H4 cell and the low endogenous ARHGEF16 level in U87 cell, sh-Control and sh-ARHGEF16 U118 stable cell lines were inoculated in athymic nude mice as described in methods section to determine ARHGEF16-knockdown effects on glioma progression." (PMID 30305138, 2018). "Our finding that ARHGEF16 is a target of GLI2 provides the first evidence of potential cross-talk between the Hh and Ephrin signaling pathways in glioma development." (PMID 30305138, 2018). "In contrast to the promoting effect of GLI2A overexpression on glioma xenograft growth, both GLI2 inhibition and ARHGEF16 knockdown retarded tumor growth." (PMID 30305138, 2018). "To investigate the role of CKAP5 in the glioma-promoting functions of ARHGEF16, we knocked down CKAP5 while overexpressing ARHGEF16 in U87 glioma cells." (PMID 30305138, 2018).
glioma (continued). "Based on these results, we selected ARHGEF16 as a candidate gene regulated by GLI2 affecting cell proliferation and migration in glioma." (PMID 30305138, 2018). "Further studies have shown that ARHGEF16 activates RhoG and PI3K, contributing to apoptosis resistance in tumor cells, and interacts with CKAP5 to promote the proliferation and migration of glioma cells." (PMID 35680563, 2022).
breast carcinoma (3 papers, 2018 to 2022). "ARHGEF16 (also known as Ephexin4, GEF16, or NBR) is a GEF that can activate RhoG, Rac1, and Cdc42 proteins of the Rho GTPase family and thereby promote migration and resistance to apoptosis of breast cancer cells independent of Ephrin signaling." (PMID 30305138, 2018).
colon cancer (3 papers, 2020 to 2024). "In this study, we investigated the effects of ARHGEF16 on the progression of colon cancer cells in vitro and in vivo and found that overexpression of ARHGEF16 caused marked increases in the proliferation and migration of colon cancer cells in vitro and in vivo." (PMID 32811808, 2020). "In contrast, knocking down ARHGEF16 expression reduced the proliferation, migration, and invasion of colon cancer cells." (PMID 32811808, 2020). "To examine the effect of saracatinib on the ability of ARHGEF16-induced colon cancer cell proliferation, we first performed colony formation assays." (PMID 32811808, 2020). "We further validated that ARHGEF16 promoted proliferation and migration in colon cancer cells, which were strongly dependent on FYN." (PMID 32811808, 2020). "The expression of ARHGEF16 in colon cancer samples was positively correlated with the degree of differentiation (P = 0.016)." (PMID 32811808, 2020). "We also showed that ARHGEF16-induced colon cancer cell proliferation and migration were tightly dependent on FYN." (PMID 32811808, 2020). "We also found that ARHGEF16 levels were highly correlated with tumor differentiation in colon cancers by analyzing clinical colon cancer specimens." (PMID 32811808, 2020). "We further analyzed the correlations between the expression of ARHGEF16 and the clinical and pathological features of patients with colon cancer." (PMID 32811808, 2020). "In summary, our findings suggest that ARHGEF16 contributes to the proliferative ability of colon cancer cells through FYN." (PMID 32811808, 2020). "Our studies detailed below investigated the roles of FYN and ARHGEF16 and their relationship in colon cancer through in vitro experiments." (PMID 32811808, 2020). "The ARHGEF16 protein expression was also higher in colon cancer cells than in HEK293T cells or gastric cancer cells." (PMID 32811808, 2020). "FYN and ARHGEF16 interact to promote the migration of colon cancer cells." (PMID 36740671, 2023). "FYN interacts with ARHGEF16 to promote colon cancer cell proliferation." (PMID 36740671, 2023). "Knocking down FYN expression decreased ARHGEF16 protein level in colon cancer cells." (PMID 32811808, 2020). "In colon cancer cells, ARHGEF16-stimulated proliferation and migration in vitro and in vivo." (PMID 32811808, 2020). "Furthermore, we found that ARHGEF16 protein levels were significantly increased in colon cancer tissue samples compared with paired adjacent normal tissue samples as detected by immunohistochemistry (IHC)." (PMID 32811808, 2020). "Moreover, cell migration was also inhibited in ARHGEF16 + Sh-FYN HCT116 cells relative to ARHGEF16 + Sh-control HCT116 cells, suggesting that FYN is required for ARHGEF16-induced colon cancer cell migration." (PMID 32811808, 2020). "Our findings highlight the importance of ARHGEF16 in the regulation of colon cancer progression." (PMID 32811808, 2020). "In this study, we showed that ARHGEF16 was highly expressed in clinical specimens of colon cancer." (PMID 32811808, 2020). "Taken together, these results demonstrated that ARHGEF16 could be a prognostic biomarker in human colon cancer." (PMID 32811808, 2020). "However, how ARHGEF16 is regulated in response to the progression of colon cancer remains poorly understood." (PMID 32811808, 2020). "Thus, this is a novel mechanism that regulates ARHGEF16 activity involved in promoting the progression of colon cancer." (PMID 32811808, 2020). "Our findings may represent in part how ARHGEF16 is persistently activated in colon cancer cells." (PMID 32811808, 2020). "However, what is exactly FYN functions in colon cancer, including whether it works directly with ARHGEF16 to perform an oncogenic function or plays a role in tumorigenesis associated with this oncogenic function, remains unknown." (PMID 32811808, 2020). "However, it remains unclear whether there are other yet unknown ARHGEF16 signaling pathways that are important in the progression of colon cancer." (PMID 32811808, 2020).
colon cancer (continued). "FYN interacts with ARHGEF16 to regulate the proliferation and migration of colon cancer cells, and knockdown of FYN expression decreases ARHGEF16 protein levels in colon cancer cells." (PMID 36740671, 2023). "We further demonstrated that ARHGEF16-induced colon cancer cell proliferation and migration were dependent on FYN since knockdown FYN abolished the ARHGEF16-induced proliferation and migration of colon cancer cells." (PMID 32811808, 2020). "Thus, co-targeting ARHGEF16 and FYN maybe a relatively effective approach for anti-colon cancer therapy, as these molecules are highly active in and related to colon cancer." (PMID 32811808, 2020).
oligoastrocytoma (1 paper, 2011). A WHO grade II tumor composed of a conspicuous mixture of two distinct neoplastic cell types morphologically resembling the tumor cells in oligodendroglioma and diffuse astrocytoma. "The ARHGEF16 promoter does show hypermethylation on Infinium Methylation arrays (Illumina, San Diego, USA), on 68 anaplastic oligodendrogliomas and oligoastrocytomas; PF, manuscript in prep) and is correlated with loss of 1p and 19q (p = 0.035, Fisher exact test)." (PMID 21760942, 2011).
oligodendroglioma (1 paper, 2011). A well-differentiated (WHO grade II), diffusely infiltrating neuroglial tumor, typically located in the cerebral hemispheres. "No similar ARHGEF16 mutations or deletions were found in a larger set of oligodendrogliomas." (PMID 21760942, 2011). "However, no other genetic changes were detected in the ARHGEF16 gene in a panel of 32 additional oligodendrogliomas, though the promoter is frequently hypermethylated." (PMID 21760942, 2011).
prostate carcinoma (1 paper, 2022). A carcinoma that arises from epithelial cells of the prostate gland. "In prostate cancer, there was a strong enrichment of androgen signaling encompassing hyper-hydroxymethylated ARHGEF16." (PMID 36127710, 2022).
cancer (7 papers, 2015 to 2024). A tumor composed of atypical neoplastic, often pleomorphic cells that invade other tissues. "Although the critical functions of ARHGEF16 have been reported in many cancer types, the underlying mechanism of its effect on PRCA prognosis remains to be elucidated." (PMID 35680563, 2022). "IHC results indicated that the expression of the proliferation marker Ki67 and that of MMP9, which is involved in cancer invasion and metastasis, was significantly increased in the ARHGEF16-overexpressing xenograft tumors." (PMID 32811808, 2020). "ARHGEF16, encoding a nucleotide exchange factor that catalyzes the exchange of GDP nucleotides for GTP, is critical for cell proliferation, growth, and tumorigenesis in various cancers." (PMID 35680563, 2022). "Thus, ARHGEF16 is critical for cancer cell proliferation and growth as well as tumorigenesis." (PMID 32811808, 2020). "The strategies to inhibit or stabilize the interaction of ARHGEF16 and its G proteins, along with GLI2 inhibition, can be used for cancer therapy." (PMID 30305138, 2018).
tumor (4 papers, 2015 to 2022). "Dysregulation of ARHGEF16 contributes to carcinogenesis and tumor progression." (PMID 32811808, 2020). "Then, the expression of ARHGEF16 in the xenograft tumors was determined by western blotting.The overexpression of ARHGEF16 led to dramatic increases in the average tumor volume (by ∼6-fold) and the average tumor weight (by ∼3-fold) compared with control expression." (PMID 32811808, 2020). "Further studies have shown that ARHGEF16 activating RhoG and PI3K downstream of EphA2 contributes to apoptosis resistance in tumor cells." (PMID 32811808, 2020). "Then, transwell migration, EdU and soft-agar colony formation assays were employed to test effects of ARHGEF16 on glioma cancer cell migration and proliferation, and the effects of GLI2/ARHGEF16 signaling on tumor growth were examined in vivo." (PMID 30305138, 2018). "Compared to control group, the tumor xenografts of the GLI2A + sh-Control developed much more rapidly, but was significantly retarded by ARHGEF16 knockdown in GLI2A + sh-ARHGEF16 group." (PMID 30305138, 2018). "Of them, ARHGEF16 and DCLRE1B were excluded due to their unknown correlation with the tumor." (PMID 25475780, 2015).
ARHGEF16 also shares sentences with these, for which no sentence is quoted: cyst (1 paper); gastric cancer (1); kidney diseases (1); metastatic cancer (1); neuroblastoma (1).